CD33 (CD33 molecule)
Diseases named in the same sentence as CD33 in open-access papers (continued):
Sharing a sentence is not in itself a finding about the gene and the disease.
Alzheimer disease (87 papers, 2011 to 2026). A progressive, neurodegenerative disease characterized by loss of function and death of nerve cells in several areas of the brain leading to loss of cognitive function such as memory and language. "CD33 has been implicated in the pathogenesis of Alzheimer’s disease primarily through its role in inhibiting the clearance of beta-amyloid (Aβ)." (PMID 40637125, 2025). "Studies have shown that certain blood-based biomarkers, such as CRP and CD33, are causally linked to various psychiatric disorders, including schizophrenia, Alzheimer’s disease, and Parkinson’s disease." (PMID 39859234, 2025). "Variants in genes associated with immune responses, such as TREM2 (triggering receptor expressed on myeloid cells 2) and CD33, have been linked to an increased risk of neurodegenerative diseases like Alzheimer’s disease (AD) and related disorders." (PMID 40004109, 2025). "Several studies have probed the associations between CD33 and Alzheimer’s disease susceptibility, yet the precise role of CD33 in the pathogenesis of this condition remains undetermined." (PMID 40637125, 2025). "Multiple genome wide association studies (GWAS) have identified single nucleotide polymorphisms (SNPs) in CD33 that are associated with a change in the risk for Alzheimer’s disease or late onset dementia." (PMID 40043053, 2025). "The involvement of CD33 in Alzheimer’s disease is evidenced by the association between CD33 expression and disease status and dementia severity." (PMID 40637125, 2025). "Microglia express SIGLEC-3/CD33, and its polymorphisms are associated with varying risks of Alzheimer’s disease." (PMID 39349440, 2024). "Conversely, a recent computational analysis investigating the 3D structures of CD33 with rs2455069 A>G SNP suggests a potential increase in the risk of Alzheimer’s disease." (PMID 39651329, 2024). "On the other hand, rs3865444, a CD33 single-nucleotide polymorphism, was suggested to be the reason for late-onset Alzheimer’s disease." (PMID 36614305, 2023). "Genetic variations of CD33 have been implicated as a susceptibility factor of Alzheimer’s disease (AD)." (PMID 36831269, 2023). "Genome-wide association studies (GWAS) identified several genetic loci associated with increased susceptibility to late onset Alzheimer’s disease, including CD33." (PMID 36570531, 2022). "The CD33 gene encodes for a member of the sialic-acid-binding immunoglobulin-type lectin (Siglec) family, and is one of the top-ranked Alzheimer’s disease (AD) risk genes identified by genome-wide association studies (GWAS)." (PMID 35408990, 2022). "Compared with these studies, we used a stricter P value cutoff with multiple testing correction and were able to replicate associations between BIN1, CD33 and Alzheimer’s disease and those between GPNMB and Parkinson’s disease." (PMID 37118290, 2022). "TYROBP is the downstream adaptor and putative signaling partner for several receptors implicated in Alzheimer’s disease (AD), including SIRP1β, CD33, CR3, and TREM2." (PMID 36002854, 2022). "Through downstream analysis, we highlight disease-relevant, translatable pQTLs by presenting new evidence supporting protein-disease associations; most notably, CD33 and Alzheimer’s disease, GPNMB and Parkinson’s disease, and MSR1 and schizophrenia." (PMID 34857772, 2021). "These genetic studies have shown correlations between various human diseases and Siglec genes, for example the CD33 polymorphism is associated with Alzheimer’s disease." (PMID 33708213, 2021). "Siglec-mediated inhibition on cellular uptake was also observed for CD33 (Siglec-3) which inhibits uptake and clearance of amyloid beta 42 by microglia and is implicated in exacerbation of Alzheimer’s disease." (PMID 33397354, 2021).
Alzheimer disease (continued). "The recent discovery of CD33, a microglial Siglec, as a novel genetic risk factor for late-onset Alzheimer’s disease (AD), highlights the potential role of sialic acids in the development of microglial dysfunction and neuroinflammation in AD." (PMID 33867926, 2021). "CD33 is genetically linked to Alzheimer’s disease (AD) susceptibility through differential expression of isoforms in microglia." (PMID 33766097, 2021). "Recently, a polymorphic allele of CD33 (variant rs3865444(A)) was found to be negatively correlated with the risk to develop Alzheimer’s disease (AD), thus, being AD-protective for the carrier." (PMID 34188106, 2021). "CD33 rs3865444 is a promoter variant previously associated with Alzheimer’s disease, whose role in MS remains obscure." (PMID 33198164, 2020). "For CD33 (Siglec-3), we demonstrate that it recognizes both α2-3 and α2-6 sialosides in solution and on cells, which has implications for its link to Alzheimer’s disease susceptibility." (PMID 33037195, 2020). "The CD33 gene harbors a single-nucleotide polymorphism (SNP) that protects against Alzheimer’s disease (rs12459419T)." (PMID 32398742, 2020). "Polymorphism in the microglial receptor CD33 gene has been linked to late-onset Alzheimer disease (AD), and reduced expression of the CD33 sialic acid-binding domain confers protection." (PMID 31369984, 2019). "We were able to replicate known associations between splicing of exon two in CD33 and Alzheimer’s disease and splicing of exon 13 in HMGCR and LDL cholesterol." (PMID 30618377, 2019). "Many Genome Wide Association Studies (GWAS) pointed out CD33 (Siglec-3) locus as a risk factor for late onset Alzheimer’s disease (LOAD)." (PMID 31546700, 2019). "Genome-wide association studies revealed that a single nucleotide polymorphism (SNP) within the CD33 gene correlates with Alzheimer’s disease (AD) susceptibility." (PMID 31815204, 2019). "CD33 is an immunomodulatory receptor linked to Alzheimer’s disease (AD) susceptibility via regulation of phagocytosis in microglia." (PMID 31815204, 2019). "Fourth, the expression of a sialic acid-binding lectin CD33, which is a risk factor of Alzheimer’s disease, was found to increase in microglia cells in patients with Alzheimer’s disease." (PMID 30054538, 2018). "This is genetically supported by the association of microglia-specific genes, TREM2 and CD33, and late onset Alzheimer's disease." (PMID 29311768, 2017). "In the paper, we found CD33 serum level was influenced by Alzheimer’s disease GWAS SNP, where the risk allele, rs12459419-G, was associated with higher serum CD33 level." (PMID 28129359, 2017). "CD33 is an established susceptibility locus for Alzheimer’s disease, where the risk allele has been found to alter monocyte function and amyloid biology." (PMID 28129359, 2017). "For CD33, the precise physiological functions have remained unclear, but recently, genome-wide association studies have identified variants of CD33 as a major risk factor for Alzheimer's disease, suggesting an important role in neurodegeneration." (PMID 27248327, 2016). "The levels of CD33, a sialoadhesion expressed by monocytes and macrophages and recently shown to be associated with late-onset Alzheimer’s disease and the scavenger receptor CD36 varied between donors (1-74%, CD33; 8-89%, CD36)." (PMID 24341794, 2013). "Microglia play a pivotal role in recognizing amyloid β as a DAMP and triggering innate immune signaling, and although reactive astrocytes contribute to the inflammatory milieu, genetic risk factors such as TREM2 and CD33 variants implicate microglia as key players in Alzheimer's disease." (PMID 40064497, 2025). "Several studies have also indicated that among the SIGLEC receptors, SIGLEC3 (CD33) may represent a genetic risk factor for Alzheimer’s disease." (PMID 41471108, 2025). "Interestingly, higher CD33 expression in the parietal lobe is associated with advanced cognitive decline or Alzheimer’s disease status." (PMID 38632500, 2024).
Alzheimer disease (continued). "CD33, an immunomodulatory transmembrane sialic acid binding protein expressed on myeloid cells, was identified as one such genetic risk factor associated with Alzheimer’s disease." (PMID 39336795, 2024). "Notably, previous studies indicated that higher CD33 expression levels, resulting from carrying the common CD33 risk allele (rs3865444) associated with an increased chance of developing Alzheimer’s disease." (PMID 37081539, 2023). "Here, we demonstrated a correlation between an SNP variant of the CD33 gene (SNP rs2455069-A>G) and Alzheimer’s disease risk, and proposed a new hypothesis for its functional role." (PMID 35408990, 2022). "In addition, several CD20- and CD33-expressing leukocytes increased the risk of Alzheimer’s disease; CD11-expressing leukocytes increased, and CD27- and CXCR1-expressing leukocytes decreased, Parkinson’s disease risk in MR sensitivity analyses." (PMID 37118290, 2022). "Increased expression of CD33 in the brain has been suggested to be associated with increased amyloid plaque burden, while the peripheral level of CD33 in Alzheimer’s disease (AD) patients and its role in AD remain unclear." (PMID 36192375, 2022). "Importantly, variants of the TREM2 and CD33 genes are risk factors for Alzheimer’s disease (AD), probably due to impaired uptake and clearance of amyloid-β (Aβ)." (PMID 33758958, 2021). "Using two-sample Mendelian randomisation, we identify causal associations between serum CD33 and Alzheimer’s disease, GPNMB and Parkinson’s disease, and MSR1 and schizophrenia, describing their clinical potential and highlighting drug repurposing opportunities." (PMID 34857772, 2021). "Variants of CD33 are associated with Alzheimer’s disease (AD) suggesting that modulation of CD33 signaling might be beneficial in AD." (PMID 34188106, 2021). "It has been shown that Siglec-3 (CD33) and CD33-related Siglecs, including Siglec-11, belong to the top-rated factors which may confer the risk for Alzheimer’s disease (AD)." (PMID 32575400, 2020). "Moreover, from a genetic point of view, CD33 rs3865444 is a common promoter variant, which appears to modify CD33 function and has also been previously associated with the commonest neurodegenerative disease, i.e., Alzheimer’s disease (AD)." (PMID 33198164, 2020). "This suggesting rs12459419 may influence CD33 transcription, translation or post-translation control of CD33 product (Siglec-3), and in turn modify Alzheimer’s disease risk." (PMID 28129359, 2017). "The transmembrane protein CD33 is a sialic acid-binding immunoglobulin-like lectin that regulates innate immunity but has no known functions in the brain, is considered as a risk factor for Alzheimer’s disease (AD)." (PMID 24147038, 2013). "Additionally, it remains uncertain whether CD33’s association with neurodegenerative diseases extends beyond Alzheimer’s disease, which cognitive domains are most affected and the underlying mechanisms." (PMID 40637125, 2025). "As an additional supportive finding, our MR sensitivity analyses showed that several CD20- and CD33-expressing leukocytes increase the risk of Alzheimer’s disease and that CD11-expressing leukocytes may increase, and CD27- and CXCR1-expressing leukocytes may decrease, Parkinson’s disease risk." (PMID 37118290, 2022). "It was suggested that the inhibitory Siglec-3 (CD33) and Siglec-8 as well as the microglia-derived Siglec-F share the same ligand in the brain potentially contributing to Alzheimer’s disease." (PMID 41203130, 2025). "Antagonism or genetic ablation of CD33 has been proposed to treat Alzheimer’s disease, hematological cancers, and as a selection mechanism for enriching genetically altered blood cells." (PMID 40043053, 2025). "Regional brain expression of several Alzheimer-risk genes, including APOE, CD33, and SORL1, showed a strong correlation with brain metabolism, particularly in regions of the brain that are affected earliest and most severely in Alzheimer’s disease." (PMID 38469573, 2024).
Alzheimer disease (continued). "Postmortem examinations have revealed an up-regulation of CD33 expression in microglial cells in the cerebral tissues of individuals with Alzheimer’s disease." (PMID 39596378, 2024). "For instance, microglia-expressed genes CD33 and CR1, which have been associated with Alzheimer’s disease (AD) risk in genome-wide association studies, lack reliable orthologs in mice." (PMID 39514271, 2024). "A study on late-onset Alzheimer’s disease focusing on protein–protein network interactions revealed eight genes with strong associations: APOE, SORL1, APOC1, CD33, CLU, TOMM40, CNTNAP2, and CACNA1C." (PMID 39228919, 2024). "In this study, we showed that genotype-dependent interactions between CD33 and SHP-1 in human microglia and microglia-like cells provide novel insights into the molecular mechanisms underlying Alzheimer’s disease (AD) susceptibility." (PMID 39336795, 2024). "In the light of these observations, new perspectives have opened up in the study of CD33, with novel and interesting understandings of the interactions leading to late-onset Alzheimer’s disease." (PMID 35408990, 2022). "Further analysis of the mRNA level of other phagocytosis-related genes which were involved in the pathomechanism of Alzheimer’s disease demonstrated that JQ1 significantly reduced the expression of Cd33, Trem2, and Zyx." (PMID 36613460, 2022). "APOE and CD33 expressions were especially high (and SORL1 expression and FDG PET SUVR were especially low) in regions most susceptible to Alzheimer’s disease, such as para-hippocampus and entorhinal cortex." (PMID 36092303, 2022). "Genome-wide association studies (GWAS) have identified immune-related genes as risk factors for Alzheimer’s disease (AD), including TREM2 and CD33, frequently passing a stringent false-discovery rate." (PMID 34208838, 2021). "Two anti-CD33 monoclonal antibodies, Gemtuzumab Ozogamicin and Lintuzumab, were identified as promising repositioning candidates concerning Alzheimer’s disease." (PMID 32398742, 2020). "The CD33 expression level has been recently related to Alzheimer's disease pathology, autoimmune diseases such as systemic lupus erythematosus (SLE), type II diabetes, or infection." (PMID 31143782, 2019). "The role of CD33 in microglia and Alzheimer’s disease is extensively discussed in a comprehensive recent review." (PMID 31546700, 2019). "The potential implications of administering CD33—targeted CAR therapy in light of CD33 expression on microglia, and in the context of Alzheimer's disease, will have to be addressed in future studies." (PMID 30524966, 2018). "Mutations and/or differential expression of microglial specific receptors such as TREM2, CD33, and CR3 have been associated with strong increased risk for developing Alzheimer’s disease (AD)." (PMID 28612290, 2017). "Interestingly, cognitive differences conferred by CD33 SNPs were primarily related to memory, underscoring CD33’s specificity impact on Alzheimer’s disease." (PMID 40637125, 2025). "The significant effect of CD33 SNPs in those with chronic viral hepatitis might illuminate the varied findings from earlier studies, underscoring the potential impact of chronic viral hepatitis on CD33’s role in Alzheimer’s disease pathogenesis." (PMID 40637125, 2025). "The role of CD33 in the pathogenesis of Alzheimer’s disease has garnered increasing attention." (PMID 40637125, 2025). "Furthermore, CD33 deletion in a mouse model of Alzheimer’s disease was found to improve memory retention, underscoring CD33’s potential contribution to development of the disease." (PMID 40637125, 2025). "Thus, in the context of late-onset Alzheimer’s disease (LOAD), CD33 was identified as one of the initial genes associated with the disease through comprehensive genome-wide association studies." (PMID 39596378, 2024).
Alzheimer disease (continued). "Genetic variants of SIGLEC3/CD33, SIGLEC11, and SIGLEC14 have been associated with neurodegenerative diseases such as Alzheimer’s disease, while sialyltransferase ST8SIA2 and SIGLEC4/MAG have been linked to psychiatric diseases such as schizophrenia, bipolar disorders, and autism spectrum disorders." (PMID 38529039, 2024). "Therefore, new therapeutic strategies in Alzheimer’s disease aim to inhibit CD33 activity to reverse the altered microglial phagocytic function of microglia concerning amyloid-beta." (PMID 39596378, 2024). "The sialic acid–Siglec interaction systems prevent the excessive and detrimental immune responses, yet the malfunction of interaction with Siglec3/CD33, Siglec-11, and Siglec-14 have been associated with neurodegenerative diseases such as Alzheimer’s disease (AD)." (PMID 39596031, 2024). "Mendelian randomization analyses suggested causal roles for several proteins, for example, ApoE, CD33, and GRN in Alzheimer's disease, MMP‐10 in preclinical Alzheimer's disease, SIGLEC9 in amyotrophic lateral sclerosis, and CD38, GPNMB, and ADAM15 in Parkinson's disease." (PMID 36504281, 2023). "Gene mutations affecting the expression and sequence of microglial genes (e.g. TREM2, CD33, and MS4A) increase risk for Alzheimer’s disease (AD), and implicate microglia in several disease pathways including toxic protein aggregation (Aβ and tau) and neuroinflammation." (PMID 36624100, 2023). "In particular, NEFL has been reported to be a biomarker of Alzheimer disease, where CD33 may drive impaired phagocytic capacity of microglia and pose a risk for Alzheimer's disease." (PMID 37506557, 2023). "Here, we demonstrate a positive correlation between the CD33 SNP rs2455069 and Alzheimer’s disease in a cohort of patients from a region of southern Italy, and secondly, that the R69G amino acid change affects the CD33 structure in a way that alters its binding affinity for sialic acid residues." (PMID 35408990, 2022). "Higher CD33 expression corresponds to hypometabolism in the brain, which is associated with Alzheimer’s disease, though no causal relationship can be derived from the correlation." (PMID 36092303, 2022). "The shorter CD33-isoform (D2-CD33), generated as a result of alternate splicing, lacking the ligand binding domain represents a gain of function variant that reduces Alzheimer's disease risk." (PMID 33796453, 2021). "This CD33 isoform counteracts the inhibitory effect of CD33 on TREM2 in microglia and would ultimately reduce amyloid deposition and thus exert a moderate protective effect on Alzheimer’s disease and likely SVID susceptibility." (PMID 32345996, 2020). "The importance of neuroinflammation and microglia in Alzheimer’s disease has been highlighted by multiple GWAS, which have identified a number of single polymorphisms associated with risk for development of Alzheimer’s disease in several immune related genes, including TREM2, CD33, BIN1, and CR1." (PMID 31504240, 2019). "However, genetic studies yield mixed results and it is unclear whether the impact of CD33 is specific to Alzheimer’s disease or related to broader neurodegenerative processes." (PMID 40637125, 2025). "The FN1+ MG subcluster exhibits high expression of the Alzheimer’s disease risk genes ABI3, CD33, and PTK2B, suggesting that this component of CSF microglia-like cells could emerge from a specific myeloid cell response to protein aggregates accumulating in the parenchyma during neurodegeneration." (PMID 39744938, 2025). "Interestingly, several interventions targeting CD33 are also tested as potential therapies for Alzheimer’s disease (AD), as reduced cell surface CD33 levels allowed more efficient phagocytic clearance of pathogenic Amyloid beta (Aβ) and provide protection against disease." (PMID 37506557, 2023).